NLRP12 (NLR family pyrin domain containing 12)
Diseases named in the same sentence as NLRP12 in open-access papers (continued):
Sharing a sentence is not in itself a finding about the gene and the disease.
Obesity (12 papers, 2020 to 2026). Accumulation of substantial excess body fat. "Of the 22 human NLRs known to date, six proteins (NLRP3, NLRP6, NOD1, NOD2, NLRC5 and NLRP12) have been described to be associated with obesity and low-grade inflammation and one (NLRP3) with postprandial inflammation." (PMID 37239938, 2023). "Myeloid-specific depletion of Nlrp12 led to similar results compared to full body depletion, suggesting that loss of myeloid-specific Nlrp12 confers this phenotype of obesity, IR and increased pro-inflammatory signaling." (PMID 37239938, 2023). "The microbiota of NLRP12-deficient mice spontaneously promotes excessive weight gain as a model for obesity and also elicits pro-inflammatory signaling in the colon." (PMID 35572547, 2022). "This protective function of NLRP12 is microbiota dependent, and is associated with Lachnospiraceae and their metabolites, which mitigate obesity." (PMID 33255588, 2020). "Recently, NLRP12 was shown to protect against obesity by influencing the composition of the gut microbiota." (PMID 37239938, 2023). "NLRP12 is recognized as a potent mitigator of inflammation, it is a checkpoint of obesity, restrains high fat diet-induced inflammation and regulates bowel inflammation." (PMID 35158762, 2022). "NLRP12 functions as a negative regulator of noncanonical NF-κB signaling, making Nlrp12-/- mice more susceptible to gastrointestinal inflammation in the context of inflammatory bowel disease, colitis-associated cancer, and obesity as shown in previous studies." (PMID 35572547, 2022). "Although no studies have directly investigated the relationship between Erysipelotrichaceae and inflammation, some studies have found that the absence of congenital immune receptor NLRP12 can make mice prone to obesity, decrease insulin sensitivity and increase adipose tissue inflammation." (PMID 37293204, 2023).
colon cancer (11 papers, 2013 to 2024). "In this regard, Nlrp12−/− mice were shown to be highly susceptible to inflammatory diseases of intestine such as experimental colitis and colon cancer." (PMID 30150571, 2018). "Contrary to colon cancer, NLRP12 expression is significantly higher in malignant prostate as compared to their adjacent benign tissues." (PMID 31186453, 2019). "In Nlrp12−/− mice, robust p52 generation in stromal cells through the non-canonical pathway led to colon cancer associated inflammation, a hallmark for aberrant RelA activity." (PMID 25905673, 2015).
colorectal cancer (9 papers, 2019 to 2025). A primary or metastatic malignant neoplasm that affects the colon or rectum. "Allen also found that classical and non-classical NF-κB signaling pathways were activated and the body was highly susceptible to colorectal cancer in Nlrp12-/- mouse models." (PMID 37020871, 2023). "Nlrp3−/−, Nlrp6−/−, Nlrc4−/−, Nlrp1−/−, Nlrx1−/− and Nlrp12−/− mice show increased susceptibility to inflammation-induced colorectal cancer as compared to wild-type mice." (PMID 31186453, 2019). "Previous studies have shown that NLRP12 downregulates the Wnt/β-catenin pathway by interacting with STK38 to inhibit colorectal cancer." (PMID 40796546, 2025). "NLRP12 has also been reported to play a functional regulatory role in various cancers, including colorectal cancer, liver cancer, and prostate cancer, and it is associated with patient prognosis." (PMID 40796546, 2025). "NLRP12 protein expression is decreased in colorectal cancer (CRC) tissues compared to the surrounding normal tissue of the CRC patients." (PMID 31186453, 2019). "Increased NLRP12 expression associates with the progression of prostate cancer suggesting NLRP12 as potential marker to treat colorectal cancers." (PMID 31186453, 2019). "NOD1 and NOD2 expression were enhanced in colorectal cancer, and NLRC5, NLRP6 and NLRP12 had no significant changes compared to the controls." (PMID 34571825, 2021).
familial Mediterranean fever (8 papers, 2013 to 2025). Familial Mediterranean fever (FMF) is an autoinflammatory disorder characterized by recurrent short episodes of fever and serositis resulting in pain in the abdomen, chest, joints and muscles. "AIDs include cryopyrin-associated periodic syndrome (CAPS), familial Mediterranean fever (FMF), and NLRP12-related periodic fever among others." (PMID 33215255, 2021).
hepatocellular carcinoma (8 papers, 2019 to 2025). A malignant tumor that arises from hepatocytes. "NLRP12 deficiency promoted hepatocyte proliferation and increased inflammation in diethylnitrosamine induced hepatocellular carcinoma." (PMID 37658975, 2023). "This study demonstrated that Nlrp12-/- mice are highly susceptible to hepatocellular carcinoma." (PMID 31941025, 2020). "In a hepatocellular carcinoma mouse model induced by the carcinogen diethylnitrosamine, NLRP12 has been shown to hinder the progression of hepatocellular carcinoma by reducing inflammation and limiting the proliferation of hepatocytes." (PMID 39351983, 2025). "In addition, cg27281030 is located in the TSS1500 region of NLRP12, which has been demonstrated regulate inflammation, and it is believed that hepatocellular carcinoma was negatively regulated by NLRP12 through suppression of inflammation and proliferation of hepatocytes." (PMID 35097114, 2022). "In hepatocellular carcinoma (HCC), however, NLRP12 downregulates the JNK-dependent inflammation and proliferation of hepatocytes and NLRP12 deficient mice were highly susceptible to diethyl nitrosamine (DEN)-induced HCC with increased inflammation, hepatocyte proliferation and tumor burden." (PMID 34768828, 2021). "In this study, NLRP12 was lowly expressed in TNBC, and the inhibition of NLRP12 expression enhanced proliferation, migration, and invasion abilities, which is consistent with the results in hepatocellular carcinoma." (PMID 37658975, 2023). "NLRP12 reduced the progression of hepatocellular carcinoma via suppressing JNK activation but not the NF-κB, ERK, and p38 pathways." (PMID 37658975, 2023).
familial cold autoinflammatory syndrome 2 (7 papers, 2015 to 2025). An autoinflammatory disease caused by mutations in the NLRP12 gene. "NLRP12 encodes the nucleotide-binding leucine-rich repeat-containing receptor 12 protein and has been linked to familial cold autoinflammatory syndrome 2 (FCAS2)." (PMID 40225939, 2024). "Recent studies have demonstrated that NLRP12 mutations can cause a rare autosomal dominant SAID (NLRP12-AID) known as familial cold autoinflammatory syndrome 2 (FCAS2), which is mostly induced by cold." (PMID 35123508, 2022). "Mutations in NLRP12 have been linked to autoinflammatory disorders, in particular the familial cold autoinflammatory syndrome 2 (FCAS2, OMIM: 611762)." (PMID 33372854, 2021). "In humans, mutations in NLRP12 have been linked to familial cold autoinflammatory syndrome 2 (FCAS2, OMIM #611762), which is characterized by recurrent, cold-induced episodes of fever associated with various systemic symptoms, including urticaria, headache, myalgia, arthralgia, and joint swelling." (PMID 40225939, 2024). "For instance, the NLRP12:p.R284X variant, while classified as likely benign by ACMG, is labelled as pathogenic in ClinVar for the rare monogenic autosomal dominant condition of familial cold autoinflammatory syndrome 2 in childhood." (PMID 39844836, 2024).
viral infection (7 papers, 2019 to 2026). "Recent research has indicated that NLRP12 exerts negative regulation on inflammation during viral infections and impacts immune cell apoptosis." (PMID 38257759, 2023). "Together, these results unveiled a role of RUNX1 located at the NLRP12 promoter that is required to suppress the transcriptional activation of NLRP12 under IFN-I stimulation or during virus infection." (PMID 36719379, 2023). "During viral infection, NLRP12-mediated inhibition is relieved due to its reduced expression, which activates retinoic acid–inducible gene I–mediated (RIG-I–mediated) signaling." (PMID 36719379, 2023). "In conclusion, PHGDH and NLRP12 play significant roles in virus-infection-related research." (PMID 38257759, 2023). "We attributed the reduced NLRP12 expression to the nucleic acid components derived from viral infection; thus, we stimulated cells with a synthetic analog of dsRNA (poly[I:C]) or transfected cells with synthetic analogs of dsDNA sequences, such as poly(dA:dT) and poly(dG:dC)." (PMID 36719379, 2023). "Furthermore, at the clinical population level, studying the significance and value of PHGDH and NLRP12 in viral infections becomes even more imperative." (PMID 38257759, 2023). "Several studies also investigated the role of NLRP12 in modulating viral infection." (PMID 34956178, 2021). "This comprehensive review synthesizes the diversified landscape of inflammasome activation during viral infections, extending beyond the canonical NLRP3 inflammasome to include specialized sensors such as NLRP6, NLRP9, NLRP1, NLRP12, and NLRC4." (PMID 42198749, 2026). "Nonetheless, how NLRP12 senses viral infection and interacts with NLRP3 to trigger the assembly of the NLRP12 PANoptosome needs to be clarified first." (PMID 38932258, 2024). "We show that virus infection, nucleic acid, and IFN-α treatment markedly reduced NLRP12 expression by RUNX1-dependent epigenetic regulation, as observed in SLE patient–derived PBMCs." (PMID 36719379, 2023). "Considering the interaction between NLRP12 and NLRP3, as well as the role of NLRP3 in PANoptosis during viral infections, it can be predicted that PANoptosis orchestrated by NLRP12 plays a role, to varying degrees, in the context of viral infections." (PMID 38932258, 2024). "We can speculate that upon viral infection, NLRP12 dissociates from TRIM25, making NLRP12 available for its interaction with NOD2." (PMID 31803185, 2019). "Unlike NLRP3, NLRP12 expression is decreased in human macrophages following viral infections (e.g., ZIKV, dengue virus [DENV], and Japanese encephalitis virus [JEV]); it exerts antiviral properties and interacts with NLRP3 to block the activation of the human NLRP3 inflammasome." (PMID 38932258, 2024).
Yersinia pestis infection (7 papers, 2013 to 2024). "Although our understanding of the role of NLRP12 in health and disease is limited, recent data suggests that NLRP12 is crucial for the recognition of Yersinia pestis, the causative agent of plague." (PMID 38566180, 2024). "Our knowledge of the role of NLRP12 in health and disease is limited, yet recent data suggest that NLRP12 is important for the recognition of Yersinia pestis, the causative agent of plague." (PMID 23666718, 2013). "And NLRP12 is protective against Yersinia pestis infection through NLRP12's activation of the inflammasome which results in secretion of IL-18 and IL-1β." (PMID 32226298, 2020). "Both NLRP12 and IL-18 were shown to be crucial for control of Yersinia pestis infection, but NLRP12 was dispensable during infections with Klebsiella pneumoniae and Mycobacterium tuberculosis." (PMID 24273542, 2013).
autoinflammatory syndrome (6 papers, 2011 to 2025). A group of disorders of the innate immune system characterized by attacks of seemingly unprovoked inflammation without significant levels of either autoantibodies or autoreactive T cells more characteristic of autoimmune disease. "In this context, the presence of heterozygous variants in the NOD2 and NLRP12 genes, documented in our patient is also noteworthy, as both have been linked to autoinflammatory syndromes with myalgia and intestinal inflammation." (PMID 41488909, 2025). "NLRP12-associated hereditary periodic fever syndrome is a rare autoinflammatory syndrome characterized by episodic and recurrent periods of fever combined with various systemic manifestations such as myalgia, arthralgia, joint swelling, urticaria, headache and skin rash." (PMID 31660995, 2019). "However, the development of CD and subsequent treatment with TNF-α inhibitors may have augmented the effects of the NLRP12 variant on inflammasomes, leading to clinical features resembling autoinflammatory syndromes." (PMID 35538558, 2022). "IL-1β, IL-18, and IL-33 were within normal limits or undetectable, and no mutations were found in genes related to the pathogenesis of autoinflammatory syndromes (MEFV, MVK, TNFRSF1A, NLRP3, and NLRP12)." (PMID 34829952, 2021).
experimental autoimmune encephalomyelitis (6 papers, 2015 to 2022). An autoimmune demyelinating disease of the central nervous system that is produced experimentally in animals by the injection of homogenized brain or spinal cord in Freund's adjuvant. "Nlrp12 has recently been implicated in regulation of neuroinflammation in the context of a murine model of MS, experimental autoimmune encephalomyelitis (EAE)." (PMID 35313917, 2022). "For example, NLRP12-mediated inhibition of NF-κB in myeloid cells contributes to protection against intestinal inflammation and tumorigenesis, in T cells it is implicated in experimental autoimmune encephalomyelitis, and in osteocytes it is involved in osteoclast differentiation." (PMID 30990169, 2019). "The NLR, Nlrp12, has been reported to both inhibit and promote neuroinflammation in an animal model of multiple sclerosis (experimental autoimmune encephalomyelitis, EAE), where its T cell-specific role has been investigated." (PMID 35313917, 2022). "This study aims to investigate the role of NLRs in neuroinflammation, particularly to uncover the role of Nlrp12 during experimental autoimmune encephalomyelitis (EAE) development." (PMID 26521018, 2015). "Interestingly, the role of NLRP12 in inflammasome activation in the brain of murine models, including a model of experimental autoimmune encephalomyelitis, has been recently described." (PMID 31836009, 2019). "Several reports implicate Nlrp12, an intracellular PRR, in the development of a mouse MS-like disease, called Experimental Autoimmune Encephalomyelitis (EAE)." (PMID 30150571, 2018). "NLRP12 is also a negative regulator of NF-κB signaling in T-cells, and absence of NLRP12 enhances severity of experimental autoimmune encephalomyelitis." (PMID 32854642, 2020).
glioma (6 papers, 2019 to 2023). A benign or malignant brain and spinal cord tumor that arises from glial cells (astrocytes, oligodendrocytes, ependymal cells). "Wild type BV2 microglia showed significantly reduced migration towards Nlrp12 deficient LN18 glioma cell culture supernatants in comparison to conditioned media from scrambled siRNA treated LN18 glioma cell culture supernatants." (PMID 31186453, 2019). "We found that Nlrp12 deficient microglia show increased colony formation while Nlrp12 deficient glioma cells show decreased cellular proliferation." (PMID 31186453, 2019). "We tested migration of microglia and glioma cells towards conditioned media from glioma cell or microglia cells derived from Nlrp12 deficient cells." (PMID 31186453, 2019). "In addition, in glioma cells, overexpression of NLRP12 and NLRC4 inflammasome-associated genes and proteins contributed to malignancy and poor prognosis." (PMID 37749707, 2023). "Interestingly, microglia show reduced migration towards Nlrp12 deficient glioma cells." (PMID 31186453, 2019). "The expression of pyroptosis-related genes, including NLRC4 and NLRP12, has been found to be increased in glioma." (PMID 38002346, 2023). "In contrast, in another study, NLRP12 was strongly activated in a glioma cell line in which the SSFA2 gene was silenced." (PMID 37723542, 2023). "NLRP12 expression was high in glioma tissues, and the inhibition of NLRP12 decreased proliferation in glioma cells." (PMID 37658975, 2023). "Pyroptosis-related gene expression, including NLRC4 and NLRP12, has been found to be increased in glioma." (PMID 38002346, 2023). "Our TCGA glioma findings show significant differential NLRP12 gene regulation and high prognostic value, which motivated us to examine the expression and functional association of NLRP12 with glioma." (PMID 31186453, 2019). "To understand the role of NLRP12 in microglia and glioma cell proliferation, we performed colony formation assay utilizing NLRP12 siRNA." (PMID 31186453, 2019). "Our study merits further investigations in vivo models of glioma initiation and progression to further tease the relative contribution of NLRP12 at a cellular and molecular level in the heterogeneous population of glioma." (PMID 31186453, 2019). "These preliminary findings suggests cell specific role of NLRP12 in glioma as indicated by the colony forming assay, immunocytochemistry and immunohistochemistry experiments." (PMID 31186453, 2019). "Using immunofluorescence, we have characterized NLRP12 expression in LN18 glioma and BV2 microglia cell lines." (PMID 31186453, 2019). "Our study identifies NLRP12 as a candidate prognostic marker for glioma progression." (PMID 31186453, 2019). "Additionally, staining of human glioma and normal brain tissue showed colocalization of NLRP12 with microglia." (PMID 31186453, 2019). "Immunohistochemistry of human glioma tissue shows increased NLRP12 expression." (PMID 31186453, 2019). "We have observed high HR (greater or equal to 0.5) for NLRC4, CASP1, NLRP12 and MSR1 genes in grade 3 & grade 4 glioma." (PMID 31186453, 2019). "Furthermore, the expression levels of genes encoding NLR proteins (NLRP12, NOD2, NOD1, NLRC4, and NAIP), inflammasome adaptor molecules (PYCARD), and proinflammatory caspases (CASP1, CASP4, and CASP5) were significantly higher in glioma patients than in normal controls." (PMID 31133717, 2019). "Moreover, Nlrp12 deficient glioma cells show lack of growth." (PMID 31186453, 2019). "Bright field imaging and quantitative analysis of Giemsa-stained microglia shows increased colony formation upon NLRP12 inhibition while LN18 glioma cell showed reduced proliferation." (PMID 31186453, 2019). "However, the roles of CASP1, NOD1, NLRC4 and NLRP12 are not reported in relation to glioma." (PMID 31186453, 2019).